MTOR (mechanistic target of rapamycin kinase)
Diseases named in the same sentence as MTOR in open-access papers (continued):
Sharing a sentence is not in itself a finding about the gene and the disease.
cancer (continued). "The mitochondrial pathway of apoptosis is also activated by mTOR signaling that belongs to survival programs that are stimulated in cancers and promote cell survival by inhibiting apoptosis." (PMID 36555740, 2022). "Many oncogenes and tumor suppressors are regulated via the PI3K/AKT/mTOR signaling pathway in various cancers, and aberrant activation of this pathway allows cancer cells to achieve high levels of signaling with minimal dependence on extrinsic factors." (PMID 36227691, 2022). "Due to its role as a major modulator of cell growth and proliferation, inhibition of mTOR has been considered as an important drug development target for cancers." (PMID 34431239, 2022). "Despite efforts, mTOR inhibitors (mTORi) have produced limited response clinically, partly due to incomplete knowledge of mTORC1 addiction in cancers." (PMID 36438486, 2022). "The expression of PI3K, Akt, and mTOR inhibits pro-apoptotic factors and activates anti-apoptotic factors to promote the occurrence and development of cancer." (PMID 35321703, 2022). "Collectively, our results demonstrate that deficiency of the LKB1-AMPK axis in cancers reactivates PROX1 to sustain intracellular BCAA pools, resulting in enhanced mTOR signalling, and facilitating tumourigenesis and aggressiveness." (PMID 36433955, 2022). "The dysregulation and incorrect activity of mTOR complexes can lead to diseases such as obesity, diabetes and even cancer." (PMID 36574435, 2022). "Rapamycin, also known as sirolimus, shows its unique inhibitory effects by binding to MTOR and has been used extensively in transplantation to prevent organ rejection, and recently, its application has expanded to cancer therapy." (PMID 35159256, 2022). "Pictilisib (GDC-0941) is a well-known dual inhibitor of class I PI3K and mTOR and is presently undergoing phase 2 clinical trials for cancer treatment." (PMID 36014303, 2022). "The exosomes carrying let-7a were found to promote a metabolic shift towards enhanced mitochondrial oxidative phosphorylation in macrophages by suppressing insulin-Akt-mTOR signaling to enhance cancer progression." (PMID 36176760, 2022). "Further IPA pathway analyses indicated that multiple cancer-associated pathways, such as transforming growth factor-β (TGF-β), mTOR, IGF-1, nuclear factor-κB (NF-κB) and phosphatase and tensin homolog (PTEN) pathways, were correlated with CPSF6 expression." (PMID 36446361, 2022). "Furthermore, inhibition of mTOR causes hyper-activation of MAPK pathway through feedback loops suggesting that combined use of inhibitors of the two pathways may be more efficient in cancer treatment." (PMID 36581900, 2022). "The PI3K/AKT/mTOR signaling pathway is one of the most frequently identified pathways in human cancer and plays a key role in driving tumor initiation and progression." (PMID 36033461, 2022). "We were able to demonstrate that the inhibition of the mTOR pathway is an effective approach for treating cancer, and the research interest in inhibitors of this pathway has increased as a result." (PMID 36077992, 2022). "In contrast, Rheb, a downstream target of the TSC1/TSC2 complex, is overexpressed in human cancers, and transgenic mice with Rheb overexpression in prostate exhibit mTOR hyperactivation and develop high grade PIN." (PMID 36180910, 2022). "CNI is known to promote cancer progression, however, mTOR inhibitors have potential benefits in decreasing the PTM burden in terms of virus-associated malignancies and anticancer properties." (PMID 36003907, 2022). "The stability and activity of mTOR complexes depend on interaction with PA and result in signals for cancer cell survival." (PMID 35250970, 2022). "In organismal aging, cancer and cellular senescence, the same key signaling pathways, such as mTOR, are involved." (PMID 35533376, 2022). "mTOR is estimated to be hyperactivated in over 70% of cancers and its hyperactivation leads to tumor growth metastasis and angiogenesis." (PMID 35078427, 2022).
cancer (continued). "In certain cancer cells, the mTOR signalling pathway is chronically hyperactivated leading to tumour growth." (PMID 35301826, 2022). "Our findings support the use of a dual PI3K/mTOR inhibitor via topical and systemic modes of delivery to prevent cancer progression to tumors in mice starting with normal histology and low-grade anal dysplasia." (PMID 36683775, 2022). "The PI3K/Akt/mTOR signaling pathway regulates the growth of both normal and cancer cells and has been shown to be hyperactivated in cancer cells." (PMID 36145724, 2022). "mTOR pathway plays a central role in regulating cancer progression and is controlled by multiple mechanisms in addition to AKT signaling." (PMID 34903601, 2022). "The PI3K/AKT/mTOR signalling pathway plays a crucial role in oncogenesis by promoting cancer cell survival, proliferation motility and invasion." (PMID 35877237, 2022). "The findings from cancer hallmarks analysis illustrated that the LMR-lncRNA signature in the high-risk group triggered MYC targets, glycolysis, hypoxia, and PI3K/AKT/mTOR signaling." (PMID 35422758, 2022). "Activation of the PIK3 leads to recruitment of the AKT kinase and subsequently intracellular cascade of phosphorylation of mTOR, a potent driver of cancer cell progression and survival." (PMID 36233758, 2022). "Compounds that can inhibit the mammalian target of rapamycin (mTOR) signaling pathway are frequently utilized to treat patients with cancer and individuals who have undergone organ transplantation." (PMID 35865820, 2022). "Ku-0063794 from KuDOS Pharmaceuticals which is now a part of AstraZeneca is another example of an ATP-competitive mTOR inhibitor with strong anti-proliferative activity against cancer cells in vitro." (PMID 36109789, 2022). "The inhibitor of the PI3K/AKT/mTOR pathway combined with radiation raises the radiosensitivity of cancer cells by activating autophagy." (PMID 35485300, 2022). "The only exception is that normal lung cell line BEAS-2B also expresses mTOR with comparable level as other cancer cells." (PMID 36077039, 2022). "Meanwhile, mTOR is a therapeutic target for tumors due to the function in promoting the synthesis of amino acids, glucose and other substances required for cancer cell growth, enabling tumors metastasis and anti-apoptosis." (PMID 35413842, 2022). "Studies have shown that the PI3K-Akt-mTOR signaling pathway plays a role in cancer cell proliferation." (PMID 35586809, 2022). "The PI3K/AKT/mTOR signaling pathway has been described as one of the most commonly disrupted pathways in cancer, making it an attractive candidate for therapeutic intervention." (PMID 35402264, 2022). "Since mTOR plays an important role in tumor progression, mTOR inhibitors are also studied in targeted cancer therapy." (PMID 36077798, 2022). "In parallel, 2-HG is reported to affect different transcription factors, such as hypoxia-inducible factor (HIF) and mammalian target of rapamycin (mTOR), which are commonly deregulated in cancer." (PMID 35740380, 2022). "In vitro characterization of lomitapide’s inhibition of mTOR and analysis of its impact in cancer cells demonstrates lomitapide’s inhibition of mTORC1." (PMID 35831271, 2022). "For example, the phosphatidylinositol 3-kinase (PI3K)/AKT/mammalian target of rapamycin (mTOR) axis alters cancer enhancing tumor cell demand for cholesterol." (PMID 35625883, 2022). "With combined treatment of LL-37 with the mTOR inhibitor rapamycin, LL-37-induced ROS production and cancer cell growth inhibition were attenuated." (PMID 35935871, 2022). "Second, the PI3K/AKT/mTOR pathway regulates cancer cell survival, proliferation, migration, and therapy response." (PMID 36295538, 2022). "Clinically, mTOR inhibitor only shows modest anticancer efficacy due to resistance and immunosuppressive properties, which suggests that mTOR inhibitors represent a therapeutic opportunity to promote the efficacy of cancer immunotherapy." (PMID 36304306, 2022).
cancer (continued). "Clinical data show that the mTOR signal is abnormally overactivated in nearly 30% of cancers and is one of the most frequently altered cascades in human cancers." (PMID 35883796, 2022). "The PI3K/AKT/mammalian target of rapamycin (mTOR) pathway is one of the most commonly activated pathways in human cancers." (PMID 36230617, 2022). "Mammalian target of rapamycin (mTOR) is a highly conserved serine-threonine kinase overexpressed in cancer." (PMID 36059548, 2022). "These molecules also disrupt the activation of MAPK and PI3K/mTOR signaling in diverse cancer cells and display anti-proliferative and anti-tumor effects." (PMID 35075146, 2022). "PF-04691502 is a novel dual PI3K/mTOR inhibitor that has antitumour effects against various cancers." (PMID 35783514, 2022). "The study outcome in the case of A549 cells involved DDP resistance and was observed in resident cancer cells due to modulation of mTOR expression." (PMID 36032679, 2022). "mTOR is an essential regulator of cancer cell response to growth factors, proliferation, and survival." (PMID 36077620, 2022). "Caffeic acid phenethyl ester (CAPE), a propolis-derived bioactive compound, shows antiproliferation to cancer cells by down-regulating PI3K/AKT/mTOR." (PMID 36139919, 2022). "As the PI3K/AKT/mTOR signaling pathway is interconnected to several cell growth and survival aspects, it is frequently activated in various cancers and can be precisely evaluated as an optimistic therapeutic target." (PMID 35313850, 2022). "The results of GSEA on the Malignant/Benign nodules RNA-seq data showed that genes related to AKT/mTOR signaling were enriched in malignant tumors compared with benign thyroid nodules." (PMID 35148777, 2022). "In recent study, the combination of SAR405 with mTOR inhibitor everolimus results in synergistic anti-proliferative activity in renal tumor cell lines, indicating its potential clinical application in cancer." (PMID 36034776, 2022). "AMPK is frequently downregulated in cancer cells, and its activation often leads to the inhibition of mTOR." (PMID 36284386, 2022). "Previous research has shown radiosensitization in response to dual PI3K/mTOR inhibitor treatment (in other cancer cell lines, both in vitro and in vivo), but an in vitro condition does not adequately depict clinical scenarios." (PMID 36555391, 2022). "In the upcoming section, we analyze how baicalein inhibited the AKT/mTOR pathway for cancer inhibition." (PMID 35955525, 2022). "The PI3K/AKT/mTOR signaling pathway has been thoroughly researched and has been shown to be important for RT resistance in different cancer types." (PMID 36555391, 2022). "Aberrant activations of the PI3K/Akt/mTOR signaling pathway are common in human cancers, including ESCC." (PMID 35392233, 2022). "Taken together, mTOR inhibition promotes drug tolerance, while activation of the mTOR pathway increases chemosensitivity, and is predictive of improved clinical survival in cancer patients." (PMID 36396656, 2022). "This inhibition of mTOR results in reduced protein synthesis and translation both with suppressed abnormal cancer cell cycle progression and proliferation." (PMID 35454306, 2022). "We brought into focus on the underlying interconnection mechanism between mTOR signaling pathway and RCC since it is conservatively known that mTOR pathway is recurrently involved in RCC through proliferation or survival of cancer cells." (PMID 36286049, 2022). "AFP is involved in multidrug resistance (MDR) by activating the PI3K/AKT/mTOR signalling pathway, which leads to metabolic reprogramming of cancer stem cells, inhibition of the expression of apoptosis‐related enzymes and resistance to tumour cell apoptosis." (PMID 36181321, 2022). "Several pharmacological inhibitors targeting the PI3K/AKT/mTOR pathway have been tested for cancer treatment and the radiosensitising potential of these inhibitors is currently being assessed in several tumour types." (PMID 35860583, 2022).
cancer (continued). "Of note, STAT3 and mTOR can strongly regulate autophagy, a catabolic process articulated in different steps that, to some extent, also helps to preserve cancer cell integrity and to resist nutrient shortage." (PMID 35681760, 2022). "The benefits of exercise and protein, both transient activators of mTOR in muscle, are well evidenced in patients with cancer." (PMID 35301826, 2022). "HIF-1α is regulated by the phosphoinositide 3-kinase (PI3K)/protein kinase B (Akt)/mammalian target of rapamycin (mTOR) pathway that controls several cellular processes including metabolism, inflammation, survival, division, and cancer progression." (PMID 35075349, 2022). "As a result, long-term sirolimus therapy blocks any beneficial signaling action relayed to Akt by mTORC2, strengthening the anti-cancer effects of mTOR inhibitors." (PMID 36109789, 2022). "The normal mTOR signalling pathway is altered in many cancers and its activity is increased in PDAC." (PMID 36289850, 2022). "In conclusion, in GBM cell lines, CLD inhibited the mTOR signaling, which is frequently dysregulated in cancers." (PMID 35159037, 2022). "We then tested the efficiency of dual PI3K/mTOR inhibitors in improving cancer cell sensitivity to radiotherapy." (PMID 35860583, 2022). "Long-term treatment in C2C12 myoblasts to IR CM was found to imitate cancer cachexia phenotype by resulting in elevated expression levels of MuRF1 and Atrogin-1 while decreasing the levels of p-mTOR and p-AKT compared with GBM CM treated group." (PMID 36231065, 2022). "Recently, a novel and promising PI3K/mTOR dual inhibitor PF-04691502 was developed, and it showed promising antitumour effects against various cancers such as colorectal cancer, B-cell non-Hodgkin's lymphomas, and head and neck cancer." (PMID 35783514, 2022). "In patients, the link between mTORC1 signalling and cachexia is not that clear; however, there are reports that suggest that the systemic use of mTOR inhibitors can aggravate cancer cachexia." (PMID 34741441, 2022). "The PI3K/AKT/mTOR pathway is persistently activated by KRAS mutation, which contributes to cancer progression." (PMID 35517800, 2022). "Previously, our group showed that Salmonella alters various signaling pathways such as mitogen-activated protein kinase (MAPK) signaling and AKT/mTOR signaling in many cancer types 36,16." (PMID 36118522, 2022). "Small-molecule inhibitors are used in targeted therapy to interfere with specific mechanisms in cancer metastasis, such as sirolimus, which inhibits mTOR expression, and copanlisib, which inhibits PI3K." (PMID 35208277, 2022). "Cell proliferation in cancer cells is stimulated by mTOR signalling in two mechanisms: by activating Akt through mTORC2 and via downregulating mTORC1 at the level of 4E-BP1." (PMID 35614940, 2022). "mTOR has been identified as a druggable target for anti-cancer treatments because it is hyperactivated in response to oncogenic signals and metabolic changes." (PMID 36180880, 2022). "Studies show that the mTOR signaling pathway is related to different diseases, such as various types of cancer." (PMID 36251702, 2022). "There is substantial evidence indicating that metformin activates AMP-activated protein kinase (AMPK), inhibits mTOR-dependent translation initiation and affects cancer cell metabolism." (PMID 36249066, 2022). "The PI3K/Akt/mTOR signaling pathway is one of the most frequently activated signal transduction pathways in human cancers." (PMID 35721193, 2022). "Inhibition of the AKT/PI3K/mTOR pathway is a vital step toward the prevention of cancer development and progression." (PMID 36144625, 2022). "Recently, treatments targeting PI3K/AKT/mTOR and mTORC1 pathways have emerged as promising strategies in cancer therapeutics." (PMID 35832194, 2022).